IL6 (interleukin 6)
Diseases named in the same sentence as IL6 in open-access papers (continued):
Sharing a sentence is not in itself a finding about the gene and the disease.
infection (continued). "Specifically, SAMP8 mice showed a general increase of Il1b expression in the cerebral cortex and, most noticeably, an extreme activation of the gene expression of Il1b, Il6 and Tnf induced by LPS in the hippocampus at young age followed by null responsiveness to infection-like stimulus at old age." (PMID 33584248, 2020). "Thus, we chose IL-6 and adrenaline as targets of the pharmacological approach to further validate their roles in mediating the mortality of neonatal mice with EV-A71 infection, although IL-8 was also upregulated in infected astrocytes and brain tissue." (PMID 31857694, 2020). "However, it additionally has to be considered that during murine TB the overall impact of IL-6 appears to depend on experimental conditions such as the bacterial dose and the route of infection." (PMID 33375150, 2020). "Notably, miR-34a was able to upregulate significantly the mRNA level of IL6 in cells of both donors 48 h after infection." (PMID 32585876, 2020). "Of note, IL-6 showed the highest increase upon AdV 7 infection among the eight increased cytokines." (PMID 33072092, 2020). "Infection with Mtb in the post-drug relapse phase, however, was associated with pulmonary activation of several pro-inflammatory cytokines and chemokines that have established roles in enhancing HIV replication including IL-1β, IL-6, TNF-α, and CCL-2." (PMID 32373548, 2020). "To analyze whether reduced cytokine mRNA expression leads to lower cytokine secretion as well, we additionally analyzed IL6 expression and IL6 secretion 4 and 6 h post infection, respectively." (PMID 33250899, 2020). "They speculated that the apical release of Ad14p1 might facilitate infection of the lower respiratory tract and that increased expression of IL-6 and IP-10 and CXCL11 might contribute to the increased host inflammatory response." (PMID 32486177, 2020). "Furthermore, it was broadly demonstrated that IL-6 is involved in the recruitment of inflammatory immune cells during infection and inflammation." (PMID 33322581, 2020). "In addition, the IL-6 mRNA and protein levels increased in an AdV 7 infection dose dependent manner." (PMID 33072092, 2020). "In addition, H. ohiense induced elevated concentrations of interleukin-6 (IL-6) that peaked 8 days after infection, which closely mirrored the expansion and contraction of neutrophils." (PMID 32848006, 2020). "Again, it is noteworthy that the rate of secondary infections tended to increase in the group treated with anti-IL-6 signaling agents compared to the SOC group in patients with critical disease (pooled OR = 1.85, 95% CI 0.95–3.61, p = 0.07), despite not reaching statistical difference." (PMID 33384605, 2020). "However, in the day 6 ferret, decreases in both IFN-γ (25-fold) and IL-6 (24-fold) where observed at day 5 post-infection, coinciding with an escalation in clinical signs in this animal." (PMID 33072098, 2020). "After stratifying by Plasmodium infection density, submicroscopic infection was associated with increased peripheral concentrations of IFN-α and decreased concentrations of IL-6, while microscopic infections were associated with elevated levels of TNF, IL-10 and IL-5." (PMID 32365058, 2020). "IL-6 is a vital cytokine of the early host response to infection." (PMID 33233806, 2020). "Furthermore, WT and Trpm2−/− neutrophils showed similar levels of TNF-α and IL-6 under infection with L. monocytogenes." (PMID 32117251, 2020). "In addition, in acute murine infection IL6 was shown to drive the survival of T. cruzi infected cardiomyocytes." (PMID 33193300, 2020). "In addition, the median value changes in the IL-6 was 29.58% (IQR 16.37–55.39%) for those patients who remained infection-free and 36.45% (IQR 16.00-55.56%) for those who are re-infected (p = 0.611)." (PMID 32887615, 2020). "Furthermore, such luciferase increase was shown in an AdV 7 infection dose dependent manner, indicating that AdV 7 can transactivate IL-6 promoter." (PMID 33072092, 2020).
infection (continued). "Recent data have suggested that infection could activate an inflammatory cascade documented by an increase in CSF IL-6, which promotes anti-AP4 antibody production from plasmablasts." (PMID 32373365, 2020). "Finally, we measured plasma levels of TNF-α, IFN-γ, IL-6, and IL-1β cytokines by an ELISA to determine if systemic secretion of cytokines offers an indication of anti-parasite protective immunity after infection and re-infection." (PMID 33414785, 2020). "However, 5 days after infection (day 5), the levels of IL-6, TNF-α, and IL-1β in group ZE were significantly lower than the model group." (PMID 32486242, 2020). "In addition, B cell-derived IL-6 can contribute to antifungal Th17 immunity following infection with C. albicans." (PMID 31813764, 2020). "Indeed, IL-6 has a pleiotropic function, and it is produced in response to tissue damage and infection." (PMID 32354030, 2020). "Finally, in a murine epicutaneous infection model, S. aureus strongly upregulated transcripts of Cxcl1, Il6, and Il17, which required the presence of both human langerin and WTA β-GlcNAc." (PMID 31088921, 2019). "Indeed, increased expression of IL-1β as well as TNFα and IL-6 has been described following infection from peritoneal exudate cells and spleen cells in mice 24 hrs post-infection." (PMID 31536604, 2019). "Thus, during the acute phase of an infection when B cells differentiate to ASCs, when there is an abundance of free IL-6, ASCs signal through IL-6 through the cell surface IL-6 receptor (IL-6R)." (PMID 31572364, 2019). "IL-6 has also been observed among patients with infection and serositis." (PMID 31697750, 2019). "IL-6, a multi-directional cytokine, is a 21-kDa glycoprotein that is not only produced mainly by the macrophages and lymphocytes, but is also expressed by various cells in response to infection." (PMID 31671729, 2019). "The pro-inflammatory cytokine IL6 plays a major role in inflammation, infection and cancer." (PMID 30841512, 2019). "In addition, appropriate pro-inflammatory cytokines such as IL-1β and IL-6 contributes to the recovery of infection, but excessive accumulation of pro-inflammatory cytokines is known to cause chronic inflammation." (PMID 31718640, 2019). "TNF-α, IL-1β, and IL-6 are pro-inflammatory cytokines and early inflammatory markers of the body produced by LPS-induced macrophages, which can be secreted and released in large quantities under conditions of injury, infection and immune response." (PMID 31835323, 2019). "Our study children were not an exception, and the presence of raised IL-6 level indicates the presence of underlying infection." (PMID 31394828, 2019). "Recently, there is growing evidence that CRP plays an important role in inflammatory processes and host responses to infection including the complement pathway, apoptosis, phagocytosis, nitric oxide release, and the production of cytokines, particularly IL-6 and TNF-α." (PMID 31333451, 2019). "Interestingly, IL-1β which we noted only in HFK-2 cells at 24 h post infection can suppress IL-6 dependent signaling Notably, we observed a 30.3- or 7.1-fold increase in IL-8 production for HFK-2 cells infected with L2 or D, respectively." (PMID 32039039, 2019). "“Double peaks of IL-6” appeared in 9 out of 11 patients with life-threatening infection." (PMID 31640816, 2019). "Additionally, mast cells can be activated by inflammatory cytokines such as IL6 and raised levels of IL6, IL1β and TNFα have been reported in patients with infection and in CSU." (PMID 31528163, 2019). "However, there was an indication of an IL-6-mediated inflammatory response during infection and/or immunization." (PMID 31065302, 2019). "It was shown that BALB.B mice that are deficient for IL-6 were still susceptible to L. major infection, and they were not able to resolve their infection." (PMID 31134162, 2019). "Regarding the upregulation of IL-6, it was observed only at 96 h post-infection." (PMID 30936869, 2019).
infection (continued). "The infection induces acute peritoneal recruitment of neutrophils and other innate immune cells, and the local and systemic production of proinflammatory cytokines and chemokines (IL-1β, IL-5, IL-6, TNF-α, RANTES, MIP-1β, MCP-1, KC and IL-10)." (PMID 31024025, 2019). "The impact of the decreased IL-6 levels on protection against infection will need to be determined." (PMID 31517284, 2019). "We hypothesized that PRV-Becker infection of DRGs that innervate the site of infection, activates the production of G-CSF and IL-6 at very early times post-infection through TLR2 signaling." (PMID 31675371, 2019). "Thus, we have shown, both in vitro and in vivo, that TFP suppressed the levels of the pro-inflammatory cytokines TNF-α and IL-6 in a state of abnormal infection." (PMID 30848296, 2019). "There was also a decrease in IL-4, IL-6, IL-10, and IL-13 in the late stages of infection." (PMID 31192210, 2019). "Initial studies determined that host inflammation, including the eicosanoid PGE2 and cytokine interleukin-6 (IL-6), was synergistically exacerbated in mice challenged with the two microbes simultaneously compared to that of monomicrobial infection and correlated with a lethal outcome." (PMID 31164467, 2019). "Here, the levels of IL-4, IL-6, and IL-22 showed a similar trend during the infection period, indicating they might help to balance inflammatory reactions." (PMID 31711531, 2019). "With a depletion of GSH during infection or T2DM, this could cause NF-kB release and upregulate the production of IL-1, TNF-α, and IL-6—all inflammatory cytokines." (PMID 31888124, 2019). "Although IL-6 is necessary for proper macrophage activity, Van Heyningen’s group found that the overproduction of IL-6 can lead to macrophages’ inability to respond properly to the infection." (PMID 31888124, 2019). "Th2-like cytokines, such as IL-4 and IL-6, decayed 1 year after the infection." (PMID 30936869, 2019). "For most early stages of infections, the expression of IL-6 is elevated." (PMID 31998294, 2019). "Increased susceptibility to this infection correlated with delayed neutrophil recruitment which correlated with lower levels of the chemokines CXCL1/KC/IL-8, CXCL2/MIP-2 and depressed levels of TNF-α, IL-1, IL-6, and IL-17/IL23 in bronchoalveolar lavage fluid." (PMID 31921165, 2019). "However, in Unc93b1 mutant, and Tlr13−/− BMDMs production of IL-6 and TNFα upon infection with S. pyogenes ATCC12344 and M49 was almost abrogated at lower MOIs, indicating a non-redundant role of RNA/TLR13 recognition at low bacterial burden." (PMID 30846984, 2019). "Using microarray and CNC analysis, we found that lncSSBP1 is highly negatively correlated with IL-6 expression after TM infection, suggesting that lncSSBP1 may have a negative regulatory effect on IL-6 expression." (PMID 31998294, 2019). "Moreover, infected macrophages supplemented with AVP (1 × 10−6 M) each for 24 h showed higher intracellular bacilli at days 1 and 3 post-infection, in co-existence with decreased IL-6 in supernatants, which was totally reversed with CVP treatment." (PMID 31244771, 2019). "Only infection with L2 stimulated production of GM-CSF, IL-1β, IL-6, IL-32, and CXCL12." (PMID 32039039, 2019). "Interestingly, the increased peak of IL‐1β and IL‐6 in Ma.24‐infected RAW264.7 was earlier than Ms13 infection at 3 hours." (PMID 31596045, 2019). "For instance, TNF-α triggers local containment of infection, and IL-6, as well as IL-1β, could reduce viral replication or increase antigen processing, thus promoting specific immune response." (PMID 31156641, 2019). "Furthermore, qPCR analysis demonstrated significant induction of the immune mediator, IL-6, in response to infection with B. cepacia (p < 0.05), B. vietnamiensis (p < 0.001), B. ambifaria (p < 0.05), Ruminococcus sp." (PMID 30606251, 2019). "IL-6 and IL-8 are mediators of the acute phase response in infection." (PMID 31369593, 2019).
infection (continued). "Varying degrees of overlap in changes in serum concentrations of interferon (IFN)-γ, monocyte chemoattractant protein (MCP)-1, and interleukin (IL)-6 were observed between patas and rhesus monkeys, suggesting the presence of common and species-specific cytokine responses to infection." (PMID 30650570, 2019). "Interestingly, all three concentrations of PACAP showed a significant increase in IL-6 expression on day 1 post-infection but by day 2 this upregulation was either lost at 0.002 μM or was significantly reduced in the two higher concentrations of PACAP." (PMID 31105711, 2019). "In addition, in the livers, IFN-α1, IFN-β, TNF, and IL-1β mRNA and, in the testes, IFN-α1, IFN-β, TNF, IL-1β, and IL-6 mRNA levels increased following infection of Ifnar1−/− mice." (PMID 31511023, 2019). "Neutrophilia and the strong increase of the pro-inflammatory IL-6 cytokine, which are related to innate immunity, are a non-specific response that occurs within the first hours after tissue damage (acute and sterile inflammation) or pathogen infection." (PMID 31906092, 2019). "Infection with all strains of S. aureus induced both IL-6 and IL-8 secretion from MAC-T cells." (PMID 30992458, 2019). "Pathogen-specific responses were also observed for IL-6 and GM-CSF, which were significantly reduced during chronic NT in cerebra of only T. canis-infected or T. cati-infected mice, respectively, while IL-3 and IL-9 were decreased in both infection groups." (PMID 31315623, 2019). "Such macrophages/monocytes are unable to secrete protective concentrations of proinflammatory chemokines and cytokines (e.g. TNFA, CCR2 or IL6) at the site of infection in an attempt to attract lymphocytes during immune restoration, thus become more permissive to infection relapse." (PMID 32905461, 2019). "This is in contrast to the upregulation of proinflammatory cytokine gene expression in human macrophages after infection with L. amazonensis and L. major, such as that of Il-1b, Tnf, and Il-6, and in murine macrophages after L. major infection, in which Tnf, Il-1, and Il-6 are upregulated." (PMID 30949455, 2019). "Inhibition of TLR2 in WT BMDMs only slightly attenuated IL-6 production upon infection with S. pyogenes ATCC12344, whereas cytokine production was completely abolished in Unc93b1 mutant cells and strongly attenuated in Tlr13−/− cells upon additional blocking of TLR2." (PMID 30846984, 2019). "In summary, we found that higher neonatal WB-iron content was inversely associated with IL-6 and MBL, which may increase susceptibility to infections." (PMID 30836628, 2019). "In contrast, at 20 h after infection brain levels of IL-6 (19.30 vs. 6.76 ng/mg tissue, P = 0.004), IL-10 (0.88 vs. 0.27 ng/mg tissue, P = 0.013), MIP-2 (15.56 vs. 7.48 ng/mg tissue, P = 0.023) and KC (31.55 vs. 10.43 ng/mg tissue, P = 0.019) were increased in Cfh−/− mice compared to wt mice." (PMID 31883521, 2019). "In the porcine model, no significant change in serum IL-6 was detected during the course of infection, further suggesting that serum IL-6 may be a less promising biomarker compared to urine IL-6 for diagnosing lower UTI." (PMID 31824442, 2019). "Dam 4 exhibited an increase above baseline in IL-1β, IL-2, IL-6, IL-7, IL-15 and IL-16, and similar to Dam 2, peak levels of these cytokines were on day 14 post-infection with the exception of IL-15 (day 7); by 21 dpi, most cytokines had returned to baseline or were lower than peak levels." (PMID 30657788, 2019). "When serum IL-6 < 8.12 pg/ml, there is a high probability that the infection has been cleared." (PMID 31711522, 2019). "However, after resolution of the infection during steady state, free IL-6 levels decrease dramatically with most of it bound to the soluble IL-6 receptor (sIL-6R)." (PMID 31572364, 2019). "In addition, C. albicans-infected Dectin-1 KO mice displayed increased serum IL-12p40 and IL-6 levels, likely due to their inability to control the infection." (PMID 31447813, 2019).
infection (continued). "During the early phase of infection, Unc93b1 mutant mice displayed significantly decreased systemic IL-6 levels compared to their WT controls, indicative of an insufficient recognition of S. pyogenes by the innate immune cells, thus potentially favoring systemic dissemination." (PMID 30846984, 2019). "A robust innate immune response was observed in S. aureus infected femurs, with abundant levels of pro-inflammatory cytokines IL-1α, IL-1β, IL-6, and TNFα detectable as soon as one day after infection, similar to what has been reported in other musculoskeletal infection models." (PMID 30978245, 2019). "However, the differences were only significant for CXCL-1 and IL-6, whereas a trend was observed throughout the entire panel of mediators released in response to infection." (PMID 31274379, 2019). "Studies have shown elevated levels of IL-1β and IL-6 following infection with influenza A." (PMID 31787983, 2019). "IL-6 was the only cytokine still elevated at 12 days post-infection." (PMID 31299982, 2019). "Additionally, the serological tests (ESR, CRP and IL-6) showed poor sensitivity and specificity in predicting persisting infection before second-stage prostheses implantation." (PMID 31159792, 2019). "IL-6 is a pleotropic cytokine produced in response to tissue damage and infections." (PMID 31134045, 2019). "IL-6 can also be used as an early indicator of potentially life-threatening infection." (PMID 31802241, 2019). "The use of Bokashi preparation as feed additives also resulted in increased concentrations of pro-inflammatory cytokines TNF-α and IL-6, which increase the protective capacity of the colostrum by stimulating cellular immune mechanisms protecting the mother and neonates against infection." (PMID 29305686, 2019). "This difference is of particular interest as IL-6 has been associated with non-survival in SHFV-infected rhesus monkeys, and because decreased concentrations of IL-6 were seen in in vitro infection of monocyte-derived macrophages and dendritic cells from baboons." (PMID 30650570, 2019). "Last not least, we have to address the fact that we cannot provide data on additional inflammation markers such as procalcitonin or interleukin-6 as a study limitation since procalcitonin has a higher diagnostic accuracy than CRP and interleukin-6 increases in early infection stages inducing CRP." (PMID 30970668, 2019). "The appearance of “double peaks of IL-6” is an indicator of grade 4–5 infection." (PMID 31640816, 2019). "Unfortunately, we did not measure TNF-α in this study and can therefore only speculate that in states of infection, damage or immunological danger, IL-6 leads to low levels of Hcrt1 and induces fatigue via a TNF-α-dependent mechanism." (PMID 31101054, 2019). "Our data shows a significant association of IL-6 with functional outcome as measured by mRS in a cohort of patients not suffering from infection, further corroborating an association independent of infections." (PMID 30828313, 2019). "RB50ΔbtrS induced macrophages to produce significantly higher levels of CCL18 and IL-6 than did wild-type bacteria, suggesting the mutant might increase recruitment of B cells to the site of infection." (PMID 31889098, 2019). "LL-37 can stimulate IL-6 production in human dendritic cells and may act as both an anti and pro-inflammatory factor during the immune response to various infections." (PMID 31374901, 2019). "Moreover, the result showed that expression of IFN‐γ in trachea, kidney, and spleen, and IL‐6 expression in spleen was higher at 24 hpi following F48E9 infection than that of GD infection." (PMID 30070070, 2019). "In order to address the immune response to the infection with C. diphtheriae in BMM, Clec4e- and Myd88-deficient cells, the supernatants were collected at 2, 4 and 20 h post-infection for determination of cytokine secretion, such as G-CSF and IL-6, respectively." (PMID 31057086, 2019).